BUB1 (BUB1 mitotic checkpoint serine/threonine kinase)
Diseases named in the same sentence as BUB1 in open-access papers (continued):
Sharing a sentence is not in itself a finding about the gene and the disease.
tumor (continued). "Based on the obtained data from TCGA, BUB1 expression was significantly higher in 371 tumor tissues compared with 50 normal tissues (P<0.001)." (PMID 32269624, 2020). "CENPF, BUB1, BUB1B, KIF23 and TTK were identified as the key potential genes affecting hypoxia associated tumor stemness in this study." (PMID 33148251, 2020). "These include a number of genome maintenance genes such as MCM subunits, Plk1, Wee1, Bub1 or cyclins that are also downregulated by the vGPCR and miR-34a in our tumor model." (PMID 26871287, 2016). "Both MAD2L1 and BUB1 expression were found to be higher in tumor than in adjacent non-tumor tissues (5.97±0.66 versus 5.36±0.38 for MAD2L1, 6.80±1.14 versus 5.50±0.74 for BUB1, respectively, and both P<0.0001) in this database." (PMID 26287798, 2015). "BUB1 is important in recruiting other spindle checkpoints at the centromere and it is involved in tumor cell proliferation because its suppression determines apoptotic cell death." (PMID 21858171, 2011). "Parallel interrogation of independent MPM patient cohorts (GSE2549, GSE29211, GSE42977, and GSE163722) corroborated the enrichment of proliferation and cell cycle-related gene sets in tumors with elevated BUB1 levels, implying that high BUB1 expression promotes tumor cell proliferation in vivo." (PMID 40180891, 2025). "Inhibition of BUB1 by its inhibitor BAY‐1816032 also exhibited considerable anti‐tumour activity." (PMID 38498903, 2024). "Additionally, we generated mammary fat pad tumor xenografts in CB17/SCID mice (N = 4-10/arm) using SUM159 BUB1 CRISPR KO cell line (clone #48)." (PMID 38863037, 2024). "Moreover, Pearson correlation showed a significant relationship between the expression levels of MYB and BUB1 in patient tumours." (PMID 38112379, 2024). "Compared with BUB1‐WT cells, the BUB1‐KD cells led to fewer disseminated tumour foci." (PMID 38498903, 2024). "Moreover, a detailed analysis of BUB1 expression in different tumours revealed distinct expression levels by molecular subtype." (PMID 38396175, 2024). "Additionally, BUB1 staining of TNBC tissue microarrays demonstrated significant correlation of BUB1 protein expression with tumor grade." (PMID 38863037, 2024). "Aberrations in BUB1 can lead to chromosomal instability and promote tumor development." (PMID 38672622, 2024). "We then assessed if BUB1 expression affected tumour growth in vivo." (PMID 38498903, 2024). "High BUB1 expression correlated with tumor malignant phenotypes (P < 0.05)." (PMID 39048649, 2024). "Furthermore, we identified eight hub genes (VSNL1, TH, PCP4, IGDCC3, RAD51AP2, MUC2, BUB1, and BUB1B) that promoted tumor progression and were associated with prognosis according to the Kaplan–Meier and ROC curve analyses." (PMID 36979826, 2023). "Interestingly, BUB1 was among the top targets of this module, rendering the tumor microenvironment resistant to ICB." (PMID 37745716, 2023). "In addition, BUB1 mRNA levels were significantly increased in most types of tumor than normal tissues in the TIMER 2.0 database." (PMID 35859724, 2022). "In the same tumor tissue, the expression levels of BUB1, BUB1, and Bub3 gene showed the same trend." (PMID 34882895, 2022). "In accordance with the tendency observed in vitro, in vivo tumor growth assay showed that the hypersensitivity to DTX in circ_0004087-knocking-down group could be weakened by upregulating BUB1." (PMID 35659274, 2022). "Similarly, high BUB1 expression with higher mRNAsi score was significantly associated with the aggressive progression of HCC, such as tumor grade and vascular invasion, which reflected that the BUB1 was contributed to the progression of HCC." (PMID 35859724, 2022).
tumor (continued). "Future studies should address this issue and examine whether high BUB1 levels can drive neoplastic transformation and promote tumor aggressiveness." (PMID 34884561, 2021). "Additionally, Aurora-B hyperactivation by BUB1 overexpression was found to result in chromosome missegregation, which induced tumor formation." (PMID 34852826, 2021). "BUB1 has been identified as an oncogene in diverse types of tumours." (PMID 34337852, 2021). "Moreover, a tumour xenograft model was established to investigate the in vivo effect of BUB1 inhibition on OS tumour growth." (PMID 34337852, 2021). "Suppression of BUB1 protein could significantly reduce cell proliferation, invasion and migration, promote apoptosis of OS in vitro and inhibit tumour growth in vivo." (PMID 34337852, 2021). "We performed in vitro and in vivo experiments, further confirming that inhibition of BUB1 in OS could suppress cell proliferation, migration and invasion, and tumour growth, as well as promote cell apoptosis." (PMID 34337852, 2021). "After incorporating tumor stage and grade with BUB1 expression in the E-MTAT-4321 cohort, NMIBC patients in the BUB1 high-grade and T1 stage group showed the worst PFS, whereas those in the BUB1 low-grade and Ta stage group had the best PFS (log-rank test, p < 0.0001)." (PMID 34884561, 2021). "BUB1 has a crucial role in mitosis, and over-expressed BUB1 contributes to tumor formation." (PMID 34440557, 2021). "CDK1 and BUB1 have been proved to influence tumor progression by inducing cell cycle dysregulation." (PMID 32411535, 2020). "We also found the expression of BUB1 to be 2.5 times higher in CS tumour samples." (PMID 32564237, 2020). "Proteins encoded by CDK1, BUB1 and AURKB belong to the serine/threonine kinases family, and overexpression of them has been detected involved in various tumors prognosis via regulating tumor cell cycle." (PMID 32411535, 2020). "Other studies have also reported correlations between BUB1 expression and tumor proliferation." (PMID 32518584, 2020). "TTK, AURKA, BUB1, CDK1 and NEK2 were fundamental kinases with high node degree, which may be required for maintaining the molecular signals underlying tumor progression." (PMID 30598639, 2018). "Optimal phenotypic pre-selection, including genetic or histologic abnormalities in the tumor, or even the presence of additional congenital features as we recently identified in individuals with BUB1 and BUB3 abnormalities, may limit this heterogeneity." (PMID 26901136, 2016). "In addition, we found from publicly available data that expression of MAD2L1 and BUB1 was higher in tumor than in adjacent non-tumor tissues." (PMID 26287798, 2015). "Furthermore, independent studies of diverse tumor types have identified Bub1 as a gene whose up-regulation correlates with poor clinical prognosis." (PMID 23738901, 2013). "Notably, this applies to a compact module of cell cycle regulators, namely survivin, cyclin B1, Cdk1, Plk1, and Bub1, whose expression increased about 2-fold in tumor versus transgenic cells according to measured fold changes." (PMID 21464922, 2011). "Considering the landscape of molecular mechanisms governing MPM tumor invasiveness and their prognostic implications, particularly the epithelial-to-mesenchymal transition (EMT), we interrogated the potential nexus between BUB1 expression and EMT-associated traits." (PMID 40180891, 2025). "Additionally, analysis of BUB1 mRNA expression in the TCGA MPM dataset—as an indicator of tumor cell proliferation—revealed a strong positive correlation between BUB1 expression and well-established proliferation and cell cycle markers, Ki67, PCNA, CCNB1, and CDC20." (PMID 40180891, 2025).
tumor (continued). "Furthermore, BUB1 gene knockout enhances the cytotoxicity of 5-FU in tumor cells." (PMID 38672622, 2024). "Moreover, we determined BUB1 expression in two tumor samples and one normal sample." (PMID 35769782, 2022). "Treatment with BAY 1816032, an inhibitor of BUB1, or knockdown of BUB1 could suppress the biological activity of OS related to cell proliferation, apoptotic tolerance, migration and invasion in vitro and tumour growth in vivo, with the involvement of PI3K/Akt and ERK pathways." (PMID 34337852, 2021). "Our data support the hypothesis of a “tuning CIN to optimize tumor fitness” by elucidating a novel molecular mechanism that highlight the role of the RNA binding protein HNRNPL as the tiebreaker for the miR-155 targeting of BUB1." (PMID 31018621, 2019). "We divided cases with different frequency of BUB1 expression into “low, medium and high” based on quartiles with low expression representing any staining frequency below the 25th percentile (8% of tumor nuclei) and high expression above the 75th percentile (28% of tumor nuclei)." (PMID 29100315, 2017). "Furthermore, BUB1 expression was inversely correlated with residual tumor stage (p = 0.038)." (PMID 29100315, 2017). "The mitotic checkpoint gene, BUB1, may also drive tumor metastasis and progression." (PMID 26096802, 2015). "Among these genes, BUB1 may play a key role in regulating these genes to promote tumor formation." (PMID 24758163, 2014). "Protein expression of BUB1, STAT3, and p-STAT3 in tumor tissues was further analyzed by Western blot and immunohistochemistry (IHC)." (PMID 42164122, 2026). "The significant overlap highlights the dual roles of genes such as TOP2A, CCNB2, BUB1, TPX2, and EZH2 in both tumor initiation and tumor progression, reinforcing their potential as key biomarkers for PCa." (PMID 40626556, 2025). "Previous studies have shown that ionizing radiation affects the occurrence and development of neoplasms by disturbing these molecules, such as SP1, BUB1 and hsa-miR-513b-5p19–25." (PMID 40681531, 2025). "For example, the overexpression of BUB1 and BUB1B promotes tumor cell proliferation and metastasis by interfering with spindle assembly checkpoints in mitosis, while the knockdown of BUB1B inhibits cell proliferation, invasion, and migration in vitro." (PMID 39940833, 2025). "The analysis revealed that the five key genes, including BUB1, BUB1B, CDK1, UBE2C, and CCNA2, exhibited higher expression in LUAD tumor tissues compared to normal tissues in all cases." (PMID 41181148, 2025). "The seven genes comprising the HMR model (SUZ12, KAT2A, AURKA, BUB1, SUV39H2, UTY, and PCGF5) are critically involved in epigenetic modification, tumor progression, supporting their prognostic value in MM." (PMID 40949882, 2025). "Correlation analysis revealed a significant correlation of AURKA, AURKB, BUB1, HJURP, TOP2A, and TTK with tumor proliferation, G2M checkpoint, MYC targets, and DNA replication." (PMID 38726001, 2024). "Three PDX tumours with high (ACCX11), medium (ACCX6), and low (ACCX5M1) BUB1 expression were selected for this analysis." (PMID 38112379, 2024). "Taken together, our studies confirmed an essential role for BUB1 in promoting the growth and metastasis of ATC tumours, which were attributed to the induction of CIN through interacting with KIF14." (PMID 38498903, 2024). "We note multiple network connections between BUB1 and HDAC1, as well as connections between BUB1 and each of CDK1 (cell-cycle transition regulator) and APC (a tumor-suppressor protein within the Wnt signaling pathway)." (PMID 38030619, 2023).
tumor (continued). "Further analysis showed that overexpression of BUB1B, BUB1 and BUB3 promoted tumor cell proliferation and metastases by disturbing the spindle assembly checkpoint (SAC) in the mitosis." (PMID 37228122, 2023). "BUB1 and BUB1B mediate apoptosis in response to chromosomal aberration and inhibit the proliferation and metastasis of tumor cells." (PMID 36979826, 2023). "After analyzing the BUB1/3 mRNA expression profiles, we studied the BUB1/3 protein expression profile using the HPA and Clinical Proteomic Tumor Analysis Consortium (CPTAC) databases." (PMID 36787437, 2023). "Of note, the results revealed that BIRC5, BUB1, and TPX2 were positively correlated with tumor purity, whereas GNG7 and SST were negatively correlated with tumor purity." (PMID 36863706, 2023). "In this study, three key genes, CDC20, CCNB2, and BUB1, have been identified in youth-onset NSCLC tumor tissues based on the TCGA and GEO cohorts." (PMID 35859798, 2022). "Meanwhile, we also found that BUB3 can negatively regulate B lymphocytes, and BUB1 and BUB1B inhibit immune responses by promoting the secretion level of checkpoint molecules of the immune system, leading to immune escape of tumor cells." (PMID 35493295, 2022). "Of the SAC genes overexpressed in the OB tumor cells, TKK, PLK1, CDK1, BUB1 and BUB1B have been shown to play a role in radiosensitivity." (PMID 36482431, 2022). "Integrating the data of normal samples and tumor tissues of pancreas from GTEX and TCGA showed that BUB1 in tumor samples was significantly higher than that in normal samples." (PMID 35769782, 2022). "BUB1 and BUB1B inhibit the immune response by increasing the expression of immune checkpoint molecules, resulting in immune escape of tumor cells, which is conducive to the occurrence and development of BrCa." (PMID 35493295, 2022). "In conclusion, we found that CENPF, BUB1, BUB1B, KIF23 and TTK were potential key genes involved in regulating hypoxia induced tumor cell stemness." (PMID 33148251, 2020). "Gleason score, clinical tumor stage, lymph node involvement, margin status, NEK2, BUB1 and NCAPG in 9-genes cluster were significant by univariate Cox proportional hazard regression analysis." (PMID 31273254, 2019). "This analysis underscored canonical tumor promoting genes (e.g. cell cycle promoting genes such as CDK1 and BUB1) that were up-regulated in LUADs relative to normal lung tissues and concomitantly downstream of down-regulated TBX2 with the same gene-network." (PMID 28978111, 2017). "By multivariate Cox regression analysis we further analyzed the prognostic value of all parameters which had a p < 0.01 by univariate survival analysis (tumor stage, nodal status, UICC stage, Ki-67 expression and BUB1 expression)." (PMID 29100315, 2017). "Paired tissue analysis in 3 evaluable patients also identified PLK1, BUB1, and PBK as the top genes overexpressed in tumor relative to adjacent normal samples." (PMID 28423512, 2017). "Up regulation of the mitotic checkpoint components MAD1 or MAD2 or BUB1 is sufficient to induce CIN, suggesting that overexpression of checkpoint components play a key role in tumor formation." (PMID 27557495, 2016). "The data identified several kinases that are up-regulated in tumor cells, including; MET, PFTK1, BUB1, CKS1B, EIF2AK2, and NEK2." (PMID 22280838, 2012). "Surprisingly, that study also showed that let-7 represses several tumour suppressor genes (BRCA1, BRCA2, FANCD2, and PLAGL1, among others) and checkpoint regulators (CHEK1, BUB1, BUB1B, MAD2L1, and CDC23, among others)." (PMID 20179807, 2010). "Moreover, compared to GEM treatment alone, the combination of BUB1 knockdown and GEM treatment further reduced Ki67 staining in tumor tissues." (PMID 38672622, 2024). "Furthermore, when BUB1 knockdown was combined with GEM treatment, there was a further reduction in tumor volume and weight." (PMID 38672622, 2024).
tumor (continued). "We further investigated the roles of BUB1 and BUB1B in Ishikawa cells using siRNA and found that silencing BUB1 and BUB1B inhibited cell proliferation, migration and invasion, indicating that BUB1 and BUB1B may exhibit tumor-promoting functions in EC." (PMID 39048649, 2024). "Moreover, the expression levels of BUB1, BUB1B, CDK1, CCNA2, MCM10 were significantly higher in CRC tumor tissues compared with normal tissues based on the GEPIA database." (PMID 37466419, 2023). "One of the limitations of this study is that we have not evaluated the effect of BUB1 ablation on EGFR signaling in mouse tumor models." (PMID 37399454, 2023). "Additionally, PTX in combination with Mps1 inhibition upregulated MAD1 and Bub1 expression, potentially enhancing SAC in tumor cells." (PMID 34584572, 2021). "We found that BUB1 was related to tumor size (X2 = 11.7588, P = 0.0006) but not to age, sex, tumor grade or metastasis (P > 0.05)." (PMID 34852826, 2021). "The tumor markers CDKN2A and KRT7 were the most upregulated genes with fold changes 10.7 and 4.8, respectively, while markers for proliferation (MELK, CDK1, MKI67, CCNB2, BUB1, FOXM1, CDKN3) had fold changes spanning from 2.0–2.7." (PMID 35008799, 2021). "This complex (BUB1/BUBR1/BUB3) is necessary for correct balance of kinase-phosphatase balance during mitosis and has been proven to have a role in chromosome instability and tumor progression as well." (PMID 31311505, 2019). "BUB1 vs. TGF-β dependent signaling has important effects, which can block the phosphatidylinositol 3-kinase (PI3K)/AKT and extracellular signal-regulated kinase (ERK) signaling pathways, significantly inhibit cell proliferation, tumor growth, cell migration, and invasion." (PMID 38464517, 2024). "However, BUB1, CCNB1, BUB1B, KIF11, CDC20, TTK, and NCAPG, which are closely related to regulation of the cell cycle and DNA repair, showed strong positive correlations with tumor purity in luminal-type BC." (PMID 34733851, 2021). "Furthermore, TPX2, ZWINT, UBE2C, CCNB2, CDK1, BUB1, and BIRC5 may orchestrate the stemness, proliferation, and invasion of tumor cells." (PMID 34671679, 2021). "Therefore, future studies on BUB1 and BUB1B combining genetic approaches may provide an effective strategy for clinical anti-tumor treatment and could be the focus of SCLC research in the future." (PMID 33186389, 2020). "Overall, we identified CENPF, BUB1, BUB1B, KIF23 and TTK as potentially key genes involved in regulating hypoxia-induced tumor cell stemness, and found that AC079160.1-miR-539-5p-CENPF axis may be involved in regulating hypoxia induced tumor cell stemness in LUAD." (PMID 33148251, 2020). "Moreover, overexpression of CDK1, CCNB1, CDC20, BUB1, MAD2L1, and BUB1B in tumour tissues could increase cell proliferation and division." (PMID 33035258, 2020). "Additionally, circPVT1 represses the function of the miR-497-5p as a tumor suppressor, consequently leading to an increase in the expression of genes that regulate cell proliferation, such as aurora kinase A (AURKA) and BUB1 mitotic checkpoint serine/threonine kinase (BUB1)." (PMID 33803232, 2021). "Therefore, this study aimed to further explore the role of BUB1 in OS by investigating the effects of BUB1 inhibition using either an inhibitor of BUB1, BAY 1816032 or lentivirus‐induced knockdown on the proliferation, migration, invasion, apoptosis and tumour growth of OS." (PMID 34337852, 2021). "To validate the expression of ASMP, BUB1, CENPF, MAD2L1, NCAPG, SGO2, and TOP2A genes in tumor samples and adjoining nontumor samples, we measured their relative mRNA expressions using qPCR." (PMID 36072975, 2022). "Spearman Rho correlations analyses found moderate negative correlations between bub1 expression and the immune score, stromal score, and ESTIMATE score respectively, and a weak positive correlation between bub1 expression and the tumor purity." (PMID 36237324, 2022).